HYOU1 (hypoxia up-regulated 1)
Description:
Has a pivotal role in cytoprotective cellular mechanisms triggered by oxygen deprivation. Promotes HSPA5/BiP-mediated ATP nucleotide exchange and thereby activates the unfolded protein response (UPR) pathway in the presence of endoplasmic reticulum stress (By similarity). May play a role as a molecular chaperone and participate in protein folding.
Synonyms: ORP-150; GRP-170; GRP170; ORP150; HSP12A; IMD59
Tractability: Antibody: its Gene Ontology location is reachable by antibodies, with high confidence; UniProt predicts a signal peptide or a membrane-spanning region. PROTAC: ubiquitination databases record sites on it; its protein half-life has been measured.
Gene: Protein-coding gene on chromosome 11 (119,044,185 to 119,057,252, reverse strand). Ensembl gene ENSG00000149428.
Subcellular location: Endoplasmic reticulum lumen
Pathways (Reactome):
Cellular responses to stimuli: XBP1(S) activates chaperone genes
Disease: Maturation of DENV proteins
Vesicle-mediated transport: Scavenging by Class F Receptors
Gene Ontology:
Molecular function: protein binding; adenyl-nucleotide exchange factor activity; protein-folding chaperone binding; ATP binding; ATP hydrolysis activity
Biological process: cellular response to hypoxia; endoplasmic reticulum to Golgi vesicle-mediated transport; negative regulation of hypoxia-induced intrinsic apoptotic signaling pathway; response to endoplasmic reticulum stress; response to ischemia; negative regulation of apoptotic process; negative regulation of endoplasmic reticulum stress-induced neuron intrinsic apoptotic signaling pathway; negative regulation of intrinsic apoptotic signaling pathway; regulation of cellular response to stress; response to stress
Cellular component: endoplasmic reticulum; extracellular exosome; focal adhesion; membrane; endocytic vesicle lumen; endoplasmic reticulum chaperone complex; endoplasmic reticulum lumen; extracellular region; smooth endoplasmic reticulum
Genetic constraint (gnomAD): Loss-of-function variants: 38 observed, 121.43 expected, observed/expected ratio (o/e) 0.31, 90% interval 0.24 to 0.41. The upper end of that interval is the gene's LOEUF score, 0.41, which puts it in group 1 of 6, group 1 being the genes least tolerant of losing a copy. Missense variants: 1,077 observed, 1,323.8 expected, observed/expected ratio (o/e) 0.81, 90% interval 0.77 to 0.86. Synonymous variants: 498 observed, 500.7 expected, observed/expected ratio (o/e) 0.99, 90% interval 0.92 to 1.07.
Gene-disease validity (ClinGen):
ClinGen rates the evidence that HYOU1 causes each of these diseases.
granulocytopenia with immunoglobulin abnormality (autosomal recessive): Limited.
Homologues: Orthologues: chimpanzee HYOU1 (99% identical), macaque HYOU1 (98% identical), dog HYOU1 (92% identical), rat Hyou1 (92% identical), guinea pig HYOU1 (91% identical), mouse Hyou1 (91% identical), pig HYOU1 (91% identical), rabbit HYOU1 (91% identical), tropical clawed frog hyou1 (66% identical), zebrafish hyou1 (65% identical), Drosophila melanogaster Grp170 (39% identical), Caenorhabditis elegans T14G8.3 (32% identical). Paralogues in human: HSPA4 (24% identical), HSPH1 (24% identical), HSPA4L (23% identical), HSPA6 (20% identical), HSPA8 (20% identical), HSPA1L (19% identical), HSPA1A (19% identical), HSPA1B (19% identical), HSPA2 (19% identical), HSPA5 (19% identical), HSPA9 (15% identical), HSPA14 (13% identical), and 1 more.
Diseases named in the same sentence as HYOU1 in open-access papers:
HYOU1 is named in the same sentence as 78 diseases in open-access papers, as found by Europe PMC text mining. Sharing a sentence is not in itself a finding about the gene and the disease. The quoted sentences say what the papers report.
breast carcinoma (8 papers, 2014 to 2025). "We demonstrated that the tumor hypoxic environment increases breast cancer cells’ stemness via the overexpression of HYOU1 and hyperactivates their metabolic activity, leading to the aggressiveness of TNBC." (PMID 39201646, 2024). "Next, we tested how the overexpression of HYOU1 affects the stemness and metabolism of breast cancer cells." (PMID 39201646, 2024). "Next, a meta-analysis was performed to identify how the alteration in the HYOU1 expression level affects the aggressiveness of breast cancer." (PMID 39201646, 2024). "An in vitro study demonstrated that HYOU1 overexpression increases breast cancer cells’ stemness and hyperactivates their metabolic activity." (PMID 39201646, 2024). "We demonstrated that HYOU1 overexpression not only increases stemness but also increases the metabolic activity of breast cancer cells." (PMID 39201646, 2024). "In the current study, we used breast cancer cells with overexpressed HYOU1 to mimic a chronic hypoxia environment." (PMID 39201646, 2024). "HYOU1 has been found to be remarkably up-regulated in some human cancers such as ovarian cancers and breast cancers." (PMID 34704918, 2021). "Moreover, in the current study, we indicate that HYOU1 expression correlates with the breast cancer stage." (PMID 39201646, 2024). "Moreover, the meta-analysis demonstrated that among patients with breast cancer, HYOU1 is overexpressed predominantly at the late stage of the tumor." (PMID 39201646, 2024). "There is evidence showing that HYOU1 is overexpressed in several cancers, including breast cancer." (PMID 39201646, 2024).
diabetes (5 papers, 2014 to 2022). "Lindenmeyer and colleagues demonstrated that mRNA expression of GRP78/BiP, ORP150/HYOU1, S1P (MBTPS1), calnexin and XBP-1 increase in the kidneys of patients with established diabetes, compared with mild diabetes." (PMID 26239352, 2015).
melanoma (5 papers, 2014 to 2025). A malignant, usually aggressive tumor composed of atypical, neoplastic melanocytes. "Finally, the expression levels of CFL, GSN and HYOU1 proteins were evaluated on some representative bioptic samples from melanoma patients." (PMID 30290833, 2018).
diabetic nephropathy (4 papers, 2014 to 2023). "Up-regulation of HYOU1 and HSPA5 was found in the tubular epithelia of patients with diabetic nephropathy compared with control kidneys." (PMID 37569434, 2023).
Insulin resistance (4 papers, 2014 to 2025). Increased resistance towards insulin, that is, diminished effectiveness of insulin in reducing blood glucose levels. "High expression of HYOU1 is considered to protect ER stress and can lower insulin resistance in mice." (PMID 33807173, 2021). "Higher expression of Hyou1 is considered to be protective against ER stress and shown to reduce insulin resistance when systemically overexpressed in mice." (PMID 24505268, 2014).
ovarian carcinoma (4 papers, 2021 to 2024). A malignant neoplasm originating from the surface ovarian epithelium. "The overexpression of HYOU1 has previously been found in the prostate, non-small cell lung cancer and ovarian cancer." (PMID 39201646, 2024). "Moreover, we observed a glycoform of NATLAEQAK with oligomannose glycan N2H9, of which the gene HYOU1 was recently reported as a promotor for cell growth and metastasis via activating PI3K/AKT signaling in epithelial ovarian cancer and predicts poor prognosis." (PMID 34895137, 2021). "The application of OmicsOne on the public data set of ovarian cancer data showed that the software could confirm the previous observations consistently and discover new evidence for HNRNPU and a glycopeptide of HYOU1 as potential biomarkers for HGSOC data sets." (PMID 34895137, 2021).
COVID-19 (3 papers, 2024). A disease caused by infection with severe acute respiratory syndrome coronavirus 2. "In the validation set (GSE190496), we observed a significant increase in the gene expression levels of LSS, HYOU1, ACADVL, PRKAB2, PLIN2, AUP1, and DAP in the COVID-19 group compared to the control group." (PMID 38932215, 2024). "In sum, this study identifies seven lipophagy-related genes (ACADVL, HYOU1, DAP, AUP1, PRXAB2, LSS, and PLIN2) as biomarkers and potential therapeutic targets for COVID-19." (PMID 38932215, 2024). "The lipophagy-related genes ACADVL, HYOU1, DAP, AUP1, PRXAB2, LSS, and PLIN2 can be used as biomarkers and drug targets for COVID-19." (PMID 38932215, 2024). "A recent study reported a direct relationship between the hypoxia-inducible protein 1 (HYOU1, ORP150) and clinical characteristics of COVID-19 severity." (PMID 39861814, 2024). "Seven lipophagy-related genes, including ACADVL, HYOU1, DAP, AUP1, PRXAB2, LSS, and PLIN2, were used as biomarkers and drug targets for COVID-19." (PMID 38932215, 2024).
Hepatic steatosis (3 papers, 2022 to 2025). Steatosis is a term used to denote lipid accumulation within hepatocytes. "Intriguingly, ovariectomized (OVX) HFD-fed females exhibited obesity, glucose intolerance, insulin resistance, and moderate hepatic steatosis, linked to upregulated hepatic lipogenic (Srebf1, Scd1), β-oxidative (Cpt1a), and ER stress (Hspa5, Hyou1) genes." (PMID 40475995, 2025). "BPA exacerbated hepatic steatosis in the OVX HBPA group, elevating lipid/collagen deposition with reduced Mttp mRNA and upregulated β-oxidation (Acox1, Acadvl), mitochondrial uncoupling (Ucp2), ER stress (Hyou1, Atf6), and liver injury (Tgfb1, Casp8) genes." (PMID 40475995, 2025).
lung carcinoma (3 papers, 2017 to 2024). "Additionally, direct interaction between ECs and lung cancer cells caused an upregulation of HYOU1 in multicellular tumor spheroids (MCTSs)." (PMID 38609844, 2024). "The study found that the secretion of certain substances in response to a communication between lung cancer cells and endothelial cells (ECs) led to an increase in the expression of HYOU1 in lung cancer spheroids." (PMID 38609844, 2024). "When inhibiting HYOU1 expression, it reduced the malignant behavior and stemness of the cancer cells, facilitated apoptosis, and made the MCTSs more sensitive to chemotherapy drugs in lung cancer." (PMID 38609844, 2024). "In contrast, TSG101, involved in lung cancer cell proliferation, RAB34, HYOU1 and ACOT1 showed higher expression in AC, as compared to their levels in SCC." (PMID 29285267, 2017). "HYOU1, also known as HSP12A, GRP170 or ORP150, is over-expressed (∼60-fold) in lung cancer tissue." (PMID 29285267, 2017).
thyroid cancer (3 papers, 2016 to 2021). "To explore the molecular function of HYOU1, we investigated the expression of HYOU1 in multiple thyroid cancer cell lines, including IHH4, TPC1, K1 and BCPAP." (PMID 33792181, 2021). "In addition, the chaperon GRP170/ HYOU1 has been found to be specifically overexpressed in human breast and thyroid cancers." (PMID 28540288, 2017). "Firstly, online data from Starbase indicated the negative correlation between HYOU1 and miR‐375‐3p expression (coefficient‐R = −0.380, P = 5.95e‐19) in thyroid cancer." (PMID 33792181, 2021).
colorectal cancer (2 papers, 2013 to 2015). A primary or metastatic malignant neoplasm that affects the colon or rectum. "HYOU1 overexpression has been reported in breast and colorectal cancer tumors, and is associated with poor prognosis and metastasis into the lymphatic system." (PMID 24069324, 2013).
membranous nephropathy (2 papers, 2015 to 2021). "Studies from human kidney biopsies found that renal diseases including minimal change disease (MCD), focal and segmental glomerulosclerosis (FSGS), membranous nephropathy and DN were associated with increased podocyte ORP150/HYOU1 and GRP78 expression." (PMID 25886386, 2015).
papillary thyroid cancer (2 papers, 2021 to 2024). "However, the role of HYOU1 in papillary thyroid cancer (PTC) development and progression remains to be elucidated." (PMID 33792181, 2021).
B-cell NHL (1 paper, 2013). "Further research into the possible association of rs1804690 and B-cell NHL and a potential role for HYOU1 in lymphomagenesis would be required to confirm this relationship." (PMID 24069324, 2013).
bipolar disorder (1 paper, 2016). A disorder of the brain that causes unusual shifts in mood, energy, activity levels and the ability to carry out day-to-day tasks. "Furthermore, we also found multiple SNPs that localize to PDIA3, PDIA6 and HYOU1 that link to either BMI or bipolar disorder." (PMID 27280443, 2016).
glioma (1 paper, 2023). A benign or malignant brain and spinal cord tumor that arises from glial cells (astrocytes, oligodendrocytes, ependymal cells). "Out of these NRGs, 19 NRGs (EGLN3, HILPDA, HMBS, HYOU1, BNIP3, etc.)were found to be enriched in glioma tissues while 13 genes (SLC4A1, IL6, EPAS1, ACE, HMOX1, etc.)were decreased compared to normal tissues." (PMID 37934582, 2023).
Hypoglycemia (1 paper, 2025). A decreased concentration of glucose in the blood. "Previous reports describe patients with HYOU1 mutations presenting with combined immunodeficiency and disrupted glucose metabolism, aligning with the hypoglycemia observed in our patient." (PMID 41583281, 2025). "While homozygous HYOU1 mutations have been previously reported in patients with profound immunodeficiency, pancytopenia, and hypoglycemia, the clinical implications of heterozygous mutations remain less defined." (PMID 41583281, 2025). "We describe a patient with a heterozygous pathogenic HYOU1 mutation who presents with a longstanding history of recurrent infections, medically treated hypoglycemia, and subglottic stenosis due to repeated intubation and inflammation." (PMID 41583281, 2025). "Patients with homozygous mutations in HYOU1 have previously presented with hypoglycemia and severe, life-threatening immunodeficiencies." (PMID 41583281, 2025). "Given the patient's history of the genetic mutation, we propose that her recurrent osteomyelitis, infectious subglottic stenosis, and medically treated hypoglycemia are correlated to her pathogenic heterozygous HYOU1 mutation (exon 23, c.2638G>A) (p.Ala880Thr)." (PMID 41583281, 2025).
immunodeficiencies (1 paper, 2025). "A previous case report identified a homozygous HYOU1 mutation that presented with anemia, thrombocytopenia, and leukopenia, resulting in severe immunodeficiency, repeated infections, and ultimately death." (PMID 41583281, 2025).
lipid metabolism disorders (1 paper, 2024). "In our study, geldanamycin was found to downregulate the expression of HYOU1, inhibit lipid peroxidation, regulate lipid metabolism disorders, and exhibit antiviral, antioxidant, and anti-inflammatory activities." (PMID 38932215, 2024).
lung adenocarcinoma (1 paper, 2016). A carcinoma that arises from the lung and is characterized by the presence of malignant glandular epithelial cells. "Increased HYOU1 also positively correlated with PDIA4, a known modulator of redox status, which has been shown to promote drug resistance to cisplatin in lung adenocarcinoma." (PMID 27799870, 2016). "Of the 16 distinguishing proteins, 8 were significantly elevated in lung adenocarcinoma (COPG1, STOML2, HYOU1, PDIA4, EPRS, APEX1, LRPPRC and NANS) whereas 8 proteins were significantly decreased in lung adenocarcinoma (SPTB, SPTA1, ANK1, SLC4A1, HBG1 and HBG2)." (PMID 27799870, 2016).
nasopharyngeal carcinoma (1 paper, 2017). A carcinoma arising from the nasopharyngeal epithelium. "HYOU1 was shown to be up-regulated in breast and nasopharyngeal carcinomas, and was associated with tumor invasiveness and poor prognosis." (PMID 29285267, 2017).
nephrolithiasis (1 paper, 2024). The presence of a calculus in the pelvis of the kidney; this is most often composed of mineral salts and proteins. "Overall, studying HYOU1, HSPA5, and MANF could provide deeper insight into the role of ER stress in the pathogenesis of urolithiasis and their potential as novel targeted therapeutic approaches for nephrolithiasis." (PMID 39114033, 2024).
rectal cancer (1 paper, 2015). A primary or metastatic malignant neoplasm that affects the rectum. "The biomarker signature was comprised of seven proteins (CADM1, LGALS3BP, HYOU1, FN1, VTN, LRG1, and MRC2) (Fig4A) that could predict the localization of rectal tumors especially well (86% of subjects with rectal cancer)." (PMID 26253080, 2015).
retinal degeneration (1 paper, 2025). Degeneration of the retina. "Depletion of seven genes (Eif2s1, Hspa5, Hspa8, Nploc4, Hyou1, Ufd1, and Vcp) showed an exacerbating effect on the Rho-Pro23His retinal degeneration compared to the Cas9+/− mice." (PMID 41282224, 2025).
tumor (33 papers, 2010 to 2026). "HYOU1 is upregulated in many kinds of cancer cells, and its high expression is associated with tumour invasiveness and poor prognosis." (PMID 33792181, 2021). "HYOU1 results over-expressed in many tumors, where it appears associated with tumor invasion and with the inhibition of the drug-induced apoptosis." (PMID 28686225, 2017). "The elevation in APEX1 was paralleled by an increase in HYOU1, a heat shock protein, which has important roles in hypoxia and angiogenesis and is linked to tumor prognosis." (PMID 27799870, 2016). "Furthermore, increased HYOU1 expression is associated with tumour invasiveness and poor prognosis." (PMID 33792181, 2021). "A recent work on lung multicellular tumor spheroid revealed that the downregulation of HYOU1 suppresses the stemness and malignancy of lung cancer." (PMID 39201646, 2024). "Some of the identified proteins have been shown to inhibit apoptosis or cause tumor cells to adapt to hypoxia, thereby promoting tumor cell survival, including clusterin, CD5L, HYOU1, prosaposin, and hepatocyte growth factor activator." (PMID 35659255, 2022). "Herein, RT-qPCR was utilized for determining the levels of KCNQ1OT1, miR-296-5p and HYOU1 in clinical tumor tissue specimens and CC cell lines." (PMID 34704918, 2021). "Recent evidence suggests that HYOU1 is upregulated in a series of tumours, such as breast tumours, nasopharyngeal carcinoma, epithelial ovarian cancer and Kaposi's sarcoma." (PMID 33792181, 2021). "Elevated KCNQ1OT1 and HYOU1 as well as reduced miR-296-5p were observed in clinical tumor tissue specimens and CC cell lines." (PMID 34704918, 2021). "HYOU1 also known as oxygen-regulated protein 150 (ORP150) was upregulated in HER2 and Basal subtypes and the protein has been implicated with tumour progression in different cancers." (PMID 29954368, 2018). "In cancer, the secretion of HYOU1 enhances immunogenicity and suppresses tumor growth in murine models of melanoma and prostate cancer." (PMID 28468249, 2017). "On the contrary, further work demonstrated inhibittory effects of extracellular HSPH1 and HYOU1 upon macrophage differentiation, favoring a pro-tumor phenotype." (PMID 28468249, 2017). "Highly expressed HYOU1 induces tumor invasion, results in a poor prognosis, and inhibits apoptosis." (PMID 35678681, 2022). "To conclude, KCNQ1OT1 could aggravate the malignant behaviors of CC and facilitate tumor growth through modulating miR-296-5p/HYOU1 axis." (PMID 34704918, 2021). "Herein, results revealed that KCNQ1OT1 could aggravate the malignant behaviors of CC and facilitate tumor growth through modulating miR-296-5p/HYOU1 axis, consequently developing promising molecular targets for CC therapeutics." (PMID 34704918, 2021). "However, potential mechanism of HYOU1 in the development and progression of tumours remains largely unclear." (PMID 33792181, 2021). "Proteins that have an anti-apoptotic effect on tumor cells or mediate adaptation to hypoxia were detected: clusterin, CD5L, HYOU1, prosaposin, and hepatocyte growth factor activator." (PMID 35659255, 2022). "HYOU1 overexpression counteracted the inhibition of KCNQ1OT1 knockdown on the malignant behaviors of CC and tumor growth." (PMID 34704918, 2021). "Other genes, such as ASNS, EIF2AK4, ERMP1, and HYOU1, showed an increasing trend in tumor tissue, but this was not statistically significant." (PMID 35884393, 2022). "This hypothetical functional complex consisting of BAG3, HYOU1, GRB2, UBAP2L and DNAJB4 could be very important in PDAC since, in addition to BAG3, interactors also play an important role in tumor pathology." (PMID 35406724, 2022). "Additionally, HYOU1 overexpression abolished the suppressing effects of silenced KCNQ1OT1 on the malignant behaviors of CC cells and tumor growth." (PMID 34704918, 2021).